MALAT1 (metastasis associated lung adenocarcinoma transcript 1)
Diseases named in the same sentence as MALAT1 in open-access papers (continued):
Sharing a sentence is not in itself a finding about the gene and the disease.
hepatocellular carcinoma (continued). "In hepatocellular carcinoma, MALAT1 knockdown inhibited glucose uptake and lipogenesis by reducing the expression levels of lipidic metabolism-related genes." (PMID 35740569, 2022). "The lncRNA MALAT1 collaborates with its binding partners to regulate pre-mRNA processing and promote hepatocellular carcinoma." (PMID 36563164, 2022). "Circ-MALAT1 functions as a microRNA sponge to promote self-renewal of hepatocellular cancer stem cells." (PMID 36035170, 2022). "MALAT1 expression was significantly higher in hepatocellular carcinoma, and patients with a high expression level had a worse prognosis than those with a low expression level." (PMID 36685103, 2022). "The MALAT1-stabilized PTBP1/PSF interaction occurs in multiple cellular contexts; however, the functional module, relative to MALAT1 only, has more dominant pathological significance in hepatocellular carcinoma." (PMID 36563164, 2022). "Pearson correlation analysis showed that the level of contrast-enhanced ultrasound in patients with hepatocellular carcinoma was positively correlated with the expression level of lncRNA MALAT1 in liver cancer tissues of patients with hepatocellular carcinoma." (PMID 35706002, 2022). "Overexpression of LncRNA MALAT-1 has been demonstrated to have potential for predicting the recurrence of hepatocellular carcinoma after liver transplantation." (PMID 34905504, 2021). "Several lncRNAs, including hepatocellular carcinoma up-regulated lncRNA, NEAT1, and metastasis-associated lung adenocarcinoma transcript 1 (MALAT1), were highly expressed in liver biopsies from NAFLD patients." (PMID 34421622, 2021). "The Malat1 lncRNA is overexpressed in many types of cancers, including hepatocellular carcinoma, and induces cell proliferation in several cell lines in vitro." (PMID 33729986, 2021). "In hepatocellular carcinoma, MALAT1 can suppress the induction of apoptosis via triggering PI3K/AKT signaling." (PMID 34298879, 2021). "MALAT1 was shown to upregulate the expression of glycolytic genes which contributes the aggressive characteristics of hepatocellular carcinoma cells." (PMID 33672592, 2021). "In addition, it is reported that MALAT1 is a mutation factor associated with the occurrence of hepatocellular carcinoma (HCC)." (PMID 34821640, 2021). "For example, lncRNA MALAT1 promoted hepatocellular carcinoma development by regulating SRSF1 and activating mTOR signaling." (PMID 34240756, 2021). "miR-124-3p was antagonized by lncRNA MALAT1 in inhibiting the expression of Slug and metastasis of hepatocellular carcinoma." (PMID 33482814, 2021). "MALAT1 regulated the glucose metabolism of hepatocellular carcinoma cells by enhancing translation of metabolic transcription factor TCF7L2 through mTORC1–4EBP1 axis." (PMID 33672592, 2021). "For example, MALAT1 functioned as a competing endogenous RNA (ceRNA) by sponging miR-3064-5p, which alleviated the suppressive effect on angiogenesis in human hepatocellular carcinoma via the FOXA1/CD24/Src pathway." (PMID 34012919, 2021). "MALAT1 is capable of inducing VIM gene expression in hepatocellular carcinoma leading to the increase in migration and invasion of these cells." (PMID 35178360, 2021). "For example, MALAT1 showed a marked upregulation in lung cancer, breast cancer, colorectal cancer, bladder carcinoma, and hepatocellular carcinoma." (PMID 33450825, 2021). "Others have shown that MALAT1 interacts with multiple loci on mtDNA in hepatoma cells, and NEAT1 plays a role in DNA repair processes." (PMID 34943778, 2021). "This is consistent with the finding that the HIF-2α/MALAT1/miR-216b axis up-regulated autophagy to promote multi-drug resistance in hepatocellular carcinoma cells." (PMID 34012919, 2021). "Here, we summarize the roles of MALAT1 in liver diseases including hepatic fibrosis, hepatic carcinoma, liver regeneration, and fatty liver diseases." (PMID 35145971, 2021).
hepatocellular carcinoma (continued). "Long noncoding RNAs (lncRNAs), such as LINC00462, HOTAIR, and MALAT1, are significantly upregulated in hepatocellular carcinoma (HCC) tissues." (PMID 32554864, 2020). "Some of these lncRNAs include HOTAIR, HULC, PTV1, and MALAT1, which are also involved in the regulation of autophagy in hepatoma cells." (PMID 32473641, 2020). "Self‐renewal of hepatocellular cancer stem cells (CSCs) is found to be regulated by a circRNA, circ‐MALAT1, through a new mechanism termed mRNA braking." (PMID 32099751, 2020). "By binding and down-regulating miR-216b, MALAT1 promotes autophagy and renders hepatocellular carcinoma cell resistance to chemotherapy agents 5-fluorouracil, Adriamycin, and mitomycin C." (PMID 32174966, 2020). "Circ‐MALAT1 is highly expressed in CSCs from clinical hepatocellular carcinoma samples under the mediation of an RNA‐binding protein, AUF1." (PMID 32099751, 2020). "In hepatocellular carcinoma, MALAT1 is up-regulated and acts as a proto-oncogene via the activation of the Wnt pathway and induction of the oncogenic splicing factor SRSF." (PMID 31792655, 2020). "For example, lncRNA metastasis-associated lung adenocarcinoma transcript 1 (MALAT1) is overexpressed in various tumors, associated with metastasis and invasion, and promotes progression of hepatocellular carcinoma, osteosarcoma and bladder cancer 5-7." (PMID 33123287, 2020). "The expression of miR-142-3p in hepatocellular carcinoma cells was significantly increased by MALAT1 knockdown." (PMID 31168355, 2019). "We found that MALAT1 acted as a miRNA decoy for miR-142-3p and regulated the expression of miR-142-3p in hepatocellular carcinoma cells." (PMID 31168355, 2019). "Our study showed that the knockdown of MALAT1 inhibited the migration and invasion of hepatocellular carcinoma cells by suppressing EMT." (PMID 31168355, 2019). "In summary, we have characterized the roles of MALAT1 in hepatocellular carcinoma and specifically delineated potential molecular mechanisms." (PMID 31168355, 2019). "The role of MALAT1 in cell migration and invasion of hepatocellular carcinoma cells was further explored." (PMID 31168355, 2019). "Metastasis-associated lung adenocarcinoma transcript 1 (MALAT1), a long non coding RNA (lncRNA) present in serum, is an important biomarker for detecting hepatocellular carcinoma (HCC)." (PMID 30886644, 2019). "It has been proved that MALAT1 served as an essential prognostic biomarker for hepatocellular carcinoma after liver transplantation." (PMID 31604167, 2019). "Then, we measured the expression levels of MALAT1 and miR-142-3p in hepatocellular carcinoma cell lines and a human liver cell line." (PMID 31168355, 2019). "The upregulated expression of MALAT1 was found in almost in every organ of the digestive system including hepatocellular carcinoma tissue, but its roles and the specific molecular mechanisms are still unclear." (PMID 31168355, 2019). "Further analysis of hepatocellular carcinoma specimens demonstrated that MALAT1 expression was negatively correlated with the expression of miR-142-3p in corresponding specimens (P = 0.0004, R2 = 0.3652)." (PMID 31168355, 2019). "MALAT1 level was reported to be upregulated in hepatocellular carcinoma tissues, but its roles and the specific molecular mechanisms are still unclear." (PMID 31168355, 2019). "Overexpressed MALAT1 acts as a competing endogenous RNA sponge for miR-142-3p in hepatocellular carcinoma." (PMID 31168355, 2019). "Then, we further ascertained the role of MALAT1 in cell migration and invasion of hepatocellular carcinoma cells." (PMID 31168355, 2019). "Previous study has reported that MALAT1 is identified as an essential prognostic factor for recurrence of hepatocellular carcinoma after liver transplantation." (PMID 31604167, 2019). "LncRNA MALAT1 binds chromatin remodeling subunit BRG1 to epigenetically promote inflammation-related hepatocellular carcinoma progression." (PMID 31541081, 2019).
hepatocellular carcinoma (continued). "MALAT1 promoted cell proliferation, migration, and invasion of hepatocellular carcinoma cells by antagonizing miR-142-3p." (PMID 31168355, 2019). "MALAT1 acts as a miRNA decoy for miR-142-3p and regulates the expression of miR-142-3p in hepatocellular carcinoma cells." (PMID 31168355, 2019). "Subsequently, MALAT1 was shown to be up-regulated in a broad spectrum of tumor types, such as endometrial stromal sarcoma and hepatocellular carcinomas." (PMID 31795964, 2019). "MALAT1 is highly expressed in hepatocellular carcinoma cell lines when compared to normal liver cells, and MALAT1-miR-195-EGFR axis was found to play an important role in hepatocellular carcinoma." (PMID 31168355, 2019). "The level of MALAT1 in hepatocellular carcinoma tissues was significantly higher in lymph node metastase positive subsets than in lymph node metastase negative subsets." (PMID 31168355, 2019). "For example, our previous study revealed that MALAT1 overexpression is a predictive factor for tumour recurrence following liver transplantation in hepatocellular carcinoma." (PMID 29156758, 2017). "Recently, the mechanism and function of several lncRNAs such as HOTAIR, HULC, and MALAT1 were reported in hepatic carcinoma resulting in construction of lncRNA regulatory networks in hepatic carcinoma." (PMID 28938565, 2017). "HULC, MALAT-1, TUC338, TUC339, lncRNA-HEIH, MVIH, HOTAIR, lnc-RoR, and HOTTIP have all been associated with higher expression in hepatocellular carcinoma (HCC) compared with normal liver tissue, while MEG3 is repressed in HCC." (PMID 27007663, 2016). "MALAT1 was first shown to be over-expressed in hepatoblastomas compared to hepatocellular carcinomas, and later investigations have indicated that MALAT1 is also upregulated in colon, breast, prostate and non-small cell lung cancer (NSCLC)." (PMID 26909858, 2016). "MALAT1 can be depleted by siRNAs in hepatocellular carcinoma, leading to cell-cycle arrest and therefore decreased cell proliferation." (PMID 26556343, 2015). "After liver transplantation, MALAT1 is overexpressed in both cell lines and tissues of patients with hepatocellular carcinoma." (PMID 23843741, 2013). "LncRNA MALAT1 targets the FOXA1/CD24/Src pathway in human hepatocellular carcinoma." (PMID 39682093, 2024). "Besides, lncRNA MALAT1 controls metabolic reprogramming and regulates mitochondrial function in hepatoma carcinoma cells." (PMID 36890266, 2023). "Similarly, the lncRNA MALAT1 has been shown to promote proliferation and metastasis of hepatocellular carcinoma cells by activating the MAPK/ERK pathway." (PMID 37232821, 2023). "MALAT1 could serve as a prognostic marker for patients with hepatocellular carcinoma who have undergone liver resection." (PMID 36685103, 2022). "In addition to EMT, MALAT1 promotes metastasis by enhancing angiogenic hepatocellular carcinoma cells; VEGF-A expression and associated angiogenesis in vivo were regulated by MALAT1 in a miR-140-dependent manner." (PMID 35736633, 2022). "Moreover, MALAT1 was shown to be overexpressed in other cancers such as multiple myeloma and hepatocellular carcinoma (HCC)." (PMID 36387279, 2022). "Maybe metabolic remodeling was involved in the mitochondrial import of MALAT1 in hepatocellular carcinoma cells and retinal endothelial cells." (PMID 36551291, 2022). "Notably, lncRNA MALAT1 regulates the mTOR pathway in various tissues and tumors, especially in hepatocellular carcinoma (HCC)." (PMID 35557985, 2022). "NMD inhibition has been reported in cancer, where it leads to the stabilization of transcripts that are important for tumorigenesis, such as KLF6 (Kruppel-like factor 6) in hepatocellular carcinoma and MALAT1 (metastasis-associated lung adenocarcinoma transcript 1) in gastric cancer." (PMID 34389041, 2021).
hepatocellular carcinoma (continued). "For example, the lncRNA MALAT1, which owned the largest subnetwork and largest loss proportion, was found to regulate cancer glucose metabolism by enhancing mTOR-mediated translation of TCF7L2 in hepatocellular carcinoma." (PMID 34222227, 2021). "Moreover, a recent study demonstrated that hypoxia stimulates MALAT1 expression and that the knockdown of this lncRNA increases miR-200a-3p levels and induces apoptosis in hepatocellular carcinoma cells under hypoxic conditions." (PMID 34298879, 2021). "Herein, we explored the possibility of constructing an in situ bio-responsive self-assembled fluorescent gold-short hairpin RNA nanocomplex (Au–shRNA NCs) delivery system by co-incubating gold and MALAT1-shRNA for precise hepatocellular carcinoma (HCC) imaging and treatment." (PMID 34821640, 2021). "Moreover, Malat1 was also involved with chemoresistance in gastric cancer and multidrug resistance in hepatocellular carcinoma cells via the modulation of autophagy." (PMID 33450825, 2021). "In addition, MALAT1 binds and sponges miR-216b in fluorouracil-resistant hepatocellular carcinoma cells, and acts as a ceRNA for miR-23b-3p in chemotherapy-resistant gastric cancer cells." (PMID 32174966, 2020). "Moreover, upregulated MALAT1 is closely related to hepatocellular carcinoma (HCC) progression, and can be an independent biomarker for recurrence after liver transplantation." (PMID 33330574, 2020). "Similarly, MALAT1 expression is over two folds higher in 5-fluorouracil-resistant than parental hepatocellular carcinoma cells." (PMID 32174966, 2020). "MALAT1 was also found to regulate hepatocellular carcinoma progression through the mTOR pathway." (PMID 30781877, 2019). "Next, we explored the potential role of MALAT1 in hepatocellular carcinoma cells." (PMID 31168355, 2019). "The expression of MALAT1 was upregulated in hepatocellular carcinoma tissues." (PMID 31168355, 2019). "Collective data indicated that MALAT1 might act as a miRNA decoy for miR-142-3p and regulated the expression of miR-142-3p in hepatocellular carcinoma cells." (PMID 31168355, 2019). "Moreover, lncRNA MALAT1 was reported to be overexpressed in multiple cancer types, such as colorectal cancer, non-small cell lung cancer and hepatocellular carcinoma (HCC); its expression was also correlated with tumor progression and poor prognosis." (PMID 31448238, 2019). "MALAT1 is overexpressed in hepatocellular carcinoma (HCC) primary samples and cell lines, and its expression correlated with advanced tumor stages and reduced overall survival of HCC patients; moreover, high MALAT1 levels correlated with major risk of HCC recurrence after liver transplantation." (PMID 29739426, 2018). "For example, the extensively studied lincRNA metastasis-associated lung adenocarcinoma transcript 1 (MALAT1) is overexpressed in lung adenocarcinoma, breast, pancreatic, colon, prostate, and hepatocellular carcinomas while promoting cell proliferation and metastasis." (PMID 30557328, 2018). "It is worth mentioning that HULC plus MALAT1 may play an important role in the occurrence of hepatocellular carcinoma." (PMID 27782152, 2016). "Notably, the lncRNAs HOTTIP, H19, HOTAIR, MALAT1, antisense Igf2r (AIR), HOXA13, GTL2 (also called MEG3) and uc002mb have been reported in association with hepatocellular carcinoma (HCC)." (PMID 26172293, 2015). "Furthermore, plasma levels of HULC were increased in hepatocellular carcinoma, H19 in gastric cancer, and MALAT-1 in prostate cancer patients." (PMID 25685243, 2015). "Another lncRNA, MALAT1, is known to promote cancer metastasis in several cancer types, including lung, bladder, and cervical cancers, and its overexpression has been reported to predict tumor recurrence of hepatocellular carcinoma after liver transplantation." (PMID 24379988, 2013).
hepatocellular carcinoma (continued). "Later, a number of lncRNAs, such as HULC and MALAT1, are connected to the development of hepatocellular carcinoma (HCC) because of their functions in metastasis, apoptosis resistance, and cellular proliferation." (PMID 40868128, 2025). "For example, MALAT1 LncRNA acts as an oncogene in hepatocellular carcinoma (HCC) through the activation of mTORC1 signaling pathway." (PMID 38539200, 2024). "Contrast-enhanced ultrasound (CEUS) grading was positively correlated with lncRNA MALAT1 in patients with hepatocellular carcinoma (HCC)." (PMID 35706002, 2022). "This study aimed to explore the specific pathogenesis of lncRNA MALAT1 promoting the invasion and metastasis of hepatocellular carcinoma (HCC) through peripheral blood vessels by regulating the expression of miRNA-613 molecule." (PMID 35706002, 2022). "Moreover, the aberrant expressions of some lncRNAs mentioned in this review have also been shown to underlie the onset and pathogenesis of other cancers, such as MALAT1 and SNHG14, which seem to be possible diagnostic and prognostic therapeutic biomarkers in colorectal and hepatocellular cancer." (PMID 36558998, 2022). "MiR-3064-5p exerted an antiangiogenic role by targeting the FOXA1/CD24/Src pathway in hepatocellular carcinoma (HCC) but oncogenic lncRNA MALAT1 acted as a ceRNA to sponge miR-3064-5p." (PMID 34350110, 2021). "We aimed to elucidate the diagnostic efficacy of eight serum lncRNAs HULC, MALAT1, Linc00152, PTENP1, PTTG3P, SPRY4-IT1, UBE2CP3, and UCA1 and their combinations for the diagnosis of hepatocellular carcinoma (HCC)." (PMID 32733618, 2020). "In hepatocellular carcinoma (HCC), MALAT1-upregulated SRSF1 enhances the isoforms of the antiapoptotic gene BIM and the oncogenes S6K1 and TEAD1, leading to cancer cell proliferation, survival, and tumorigenesis." (PMID 32967226, 2020). "Virtually, the pro‐multiplication and anti‐apoptosis function of MALAT1 was also discoverable in other cancer cells (eg hepatocellular carcinoma and osteosarcoma), yet whether MALAT1 acted on identical signaling pathways in distinct neoplasms entailed further evidences." (PMID 31837057, 2020). "Hyperexpression of MALAT1 has been observed in many malignant tumors, including hepatocellular carcinoma (HCC)." (PMID 31466138, 2019). "Thus, the MALAT1/miR‐124‐3p/Slug axis plays an important role in hepatocellular carcinoma." (PMID 31466138, 2019). "MALAT1 is highly expressed in hepatocellular carcinoma (HCC) and acts as competing endogenous RNA (ceRNA) for miR-195." (PMID 30683916, 2019). "A recent study revealed that genetic variations in the lncRNAs HULC and MALAT1 are associated with decreased susceptibility to hepatocellular carcinoma (in persistent carriers of HBV), and these lncRNAs thus constitute two potential diagnostic biomarkers for hepatocellular carcinoma." (PMID 31636654, 2019). "We have found that MALAT1, a non-coding RNA, is over-expressed in the sera of people exposed to arsenite and in hepatocellular carcinomas (HCCs), and MALAT1 has a close relation with the clinicopathological characteristics of HCC." (PMID 26735578, 2016). "In hepatocellular carcinoma (HCC) MALAT1 overexpression is a predictive factor for tumor recurrence following liver transplantation." (PMID 25954300, 2015). "Later studies in hepatocellular carcinoma (HCC) revealed that MALAT1 was upregulated compared with normal liver tissue, and that the depletion of MALAT1 in HepG2 cells reduced cell viability, motility and invasiveness." (PMID 24932303, 2014). "Preclinical studies show that Resveratrol, a potent sirtuin-1 activator, is a well-known anticancer drug, and it is reported to induce mitophagy through the MALAT1/miR-143-3p/RRM2 axis, effectively inhibiting cancer progression in hepatocellular carcinoma." (PMID 40789840, 2025). "LncRNA MALAT1 also exhibits different functions in hepatocellular carcinoma (HCC)." (PMID 38933333, 2024).